NLRP3 (NLR family pyrin domain containing 3)
Diseases named in the same sentence as NLRP3 in open-access papers (continued):
Sharing a sentence is not in itself a finding about the gene and the disease.
COVID-19 (continued). "Additionally, it will scrutinize the ongoing research advancements concerning NLRP3 inhibitors for COVID-19 treatment, aiming to offer novel insights and potential therapeutic strategies for managing this disease." (PMID 38399989, 2024). "For example, inflammasome activation in COVID-19-infected macrophages drives a cytokine storm and inflammatory damage and inhibitors of NLRP3 could attenuate COVID-19 pathology." (PMID 38474071, 2024). "Additionally, drugs historically used for other conditions, such as chloroquine and hydroxychloroquine, are being investigated for their ability to inhibit NLRP3 activity, but their specific impacts on COVID-19 treatment warrant further evaluation." (PMID 38399989, 2024). "Amid the global response to the challenges posed by COVID-19, a comprehensive understanding of the NLRP3 inflammasome’s mechanisms and the evolving landscape of related inhibitors holds significant promise in guiding treatment approaches and curbing disease progression." (PMID 38399989, 2024). "Regular consumption of KRG as a supplement inhibits excessive activation of NLRP3 inflammasome and may alleviate the progression of severe COVID-19 symptoms." (PMID 38012459, 2024). "Overactive or dysregulated NLRP3 inflammasome activation in SARS-CoV-2-infected patients is linked to triggering cytokine storms, causing tissue damage and severe organ failure in individuals with critical COVID-19." (PMID 38251382, 2024). "Upon activation, the NLRP3 inflammasome promotes the release of pro-inflammatory cytokines, such as IL-1β and IL-18, which are key mediators of the inflammatory response seen in severe COVID-19 cases." (PMID 39720706, 2024). "Targeting of NLRP3 inflammasome pathway by selective inhibitors may reduce COVID-19-induced complications." (PMID 37796433, 2023). "HMGB1, NLRP3 and IL-6 levels were positively correlated with headache in patients with COVID-19." (PMID 37940864, 2023). "As there are currently clinical trials using NLRP3 inhibitors for PD, it can be proposed that these molecules may be beneficial for COVID-19-related neurological symptoms, especially COVID-19-related neurodegeneration." (PMID 36836893, 2023). "The severity of COVID-19 patients is correlated with the activation of the NLRP3 inflammasome." (PMID 36769328, 2023). "Finally, our results do not provide sufficient evidence to consider the expression of exosomal miR-17-5p, miR-146a-3p, and miR-223-3p as selective regulating factors of NLRP3 during the post-acute phase of COVID-19." (PMID 37685844, 2023). "NLRP3 animal models may be critical to study the pathogenesis of diseases, and an animal model based on NLRP3 has been considered to be critical in studying COVID-19 properly." (PMID 38143439, 2023). "Thus, we conducted a prospective longitudinal study, examining NLRP3 inflammasome functionality in COVID-19 ICU patients (n = 15) and bacterial septic shock patients (n = 17) during the first week of ICU hospitalization, compared with healthy donors." (PMID 38140660, 2023). "Activation of the NLRP3 inflammasome, which results in the production of active IL-1β, occurs during the early stages of RNA virus infection; it can also be induced by peripheral blood mononuclear cells from patients with moderate or severe COVID-19." (PMID 37515185, 2023). "NLRP1 and ASC may have a more critical role in the generation of the active form of IL-1β in COVID-19 patients compared to NLRP3." (PMID 37723427, 2023). "Accordingly, we detected the increased expression level of NLRP3 in alveolar macrophages and syncytium from autopsies of COVID-19 patients with severe disease, and observed the activation of NLRP3 inflammasome during the infection of PMA-treated THP1 macrophages with SARS-CoV-2 in vitro." (PMID 37920468, 2023). "As a result, the NLRP3 inflammasome may be considered as a potential target for early COVID-19 treatment in severe asthma." (PMID 36677800, 2023).
COVID-19 (continued). "Our findings may support the evidence that the NLRP3 inflammasome plays a crucial role in the innate immune response to SARS-CoV-2 virus infection due to the increased tissue expression of IL-1β in the COVID-19 group compared to the CONTROL and H1N1 groups." (PMID 36992415, 2023). "Hyperactivation of NLRP3 inflammasomes in macrophage lineage cells mediates the release of pro-inflammatory cytokines, which contributes to the uncontrolled systemic immune response and promotes the development of severe COVID-19." (PMID 36717892, 2023). "It has been reported that inflammasome activation is triggered by SARS-CoV-2 components, that its higher activation is possibly involved in COVID-19 severity, and that the specific inhibition of the NLRP3 inflammasome was able to decrease the intensity of a COVID-19-like pathology in mice." (PMID 37048165, 2023). "Thus, NLRP3 inflammasome represents an attractive target in the development of drugs for COVID-19 patients with severe manifestations." (PMID 37360532, 2023). "Significantly, melatonin has been found to inhibit the activation of the NLRP3 inflammasome, suggesting that melatonin treatment during COVID-19 or periodontal diseases could alleviate the damage observed in periodontal tissues." (PMID 37893162, 2023). "Notably, circulatory exosomes from severe COVID-19 patients were able to increase the expression of NLRP3, caspase-1 and IL-1β in endothelial cells." (PMID 37251383, 2023). "Additionally, the involvement of the NLRP3 inflammasome in both periodontitis and COVID-19 paints a complex immunological landscape." (PMID 37893162, 2023). "Targeting NLRP3 inflammasome by MCC950 could be a promising immunotherapeutic approach for treating COVID-19." (PMID 37251383, 2023). "Other genes that have been annotated in public database KEGG for their role in the COVID-19 pathway include NLRP3 (NLR family pyrin domain containing 3), MAPK10 (mitogen-activated protein kinase 10), and PIK3CD (phosphatidylinositol-4,5-bisphosphate 3-kinase catalytic subunit delta)." (PMID 36800980, 2023). "Using SARS-CoV-2 infection of transgenic mice expressing human angiotensin-converting enzyme 2 (hACE2) as a COVID-19 pre-clinical model, we established the presence of virus in the brain together with microglial activation and NLRP3 inflammasome upregulation in comparison to uninfected mice." (PMID 36316366, 2023). "Therefore, it is highly possible that viral dsRNA activates NLRP1 by binding to it through a leucine-rich repeat domain of NLRP1 and participates together with NLRP3 to the over-responses of the immune system leading to COVID-19 severe symptoms." (PMID 37360532, 2023). "Further, a Bruton tyrosine kinase (BTK) inhibitor was also found to reduce BTK-dependent activation of NF-κB and NLRP3 inflammasome, which suppressed pro-inflammatory factors production and COVID-19 cytokine storm, thereby improving the prognosis of COVID-19 patients." (PMID 37065192, 2023). "Colchicine may be used as a mediation that acts on NLRP3 infammasome-mediated cytokine storm in COVID-19." (PMID 37251383, 2023). "NRF2 activation may be a potential therapeutic approach to counteracting the NLRP3 inflammasome, which can be used for PD and COVID-19 by simultaneously reducing neuroinflammation and systemic inflammation." (PMID 36717892, 2023). "Nrf2 activators could play an essential role in reducing SARS-CoV-2 infection-induced inflammation by suppressing NLRP3 inflammasome in COVID-19." (PMID 37796433, 2023). "The infection–immune–inflammatory core of acute COVID-19, the development of NLRP3, a mild chronic inflammatory response, increased nitro-oxidative stress, lowered antioxidant defenses, and total Ca levels can be considered new drug targets to treat the physio-affective symptoms of long COVID." (PMID 36675440, 2023).
COVID-19 (continued). "Altogether, the NLRP3 inflammasome signatures in myeloid cells may represent a predictive biomarker for COVID-19 development and patient outcome and provide important guidance for therapeutic decisions involving immunoregulatory agents." (PMID 37251383, 2023). "Notably, the presence of COVID-19 in AD patients appears to exacerbate some of the AD-related pathological changes, such as increased proinflammatory cytokines, NLRP3 activation, and oxidative stress." (PMID 38259635, 2023). "Moreover, higher levels of inflammasome products, such as IL-18 and Casp1p20, correlated with the severity of the disease and poor clinical outcomes, supporting a role of the NLRP3 inflammasome in COVID-19 pathogenesis and progression." (PMID 36669831, 2023). "In a randomized controlled trial, Tranilast, a potential NLRP3 inflammasome inhibitor, was used as a complementary treatment in combination with standard therapeutic measures (e.g., antivirals and supportive care) in COVID-19 patients." (PMID 37251383, 2023). "In addition, NLRP3 inflammasome activation during COVID-19 can also be induced by DAMPs released as a result of the initial innate inflammatory process that follows the exposure to SARS-CoV-2 components." (PMID 37048165, 2023). "Antagonists or inhibitors of NLRP3 inflammasome could be effective in ameliorating COVID-19-related inflammation." (PMID 37251383, 2023). "As NLRP3 inflammasome is the potential inflammatory pathway for inflammation-related COVID-19, we determined whether nanocurcumin could inhibit the NLRP3 inflammasome pathway using the Western blot technique." (PMID 37375809, 2023). "The exact mechanisms underlying colchicine effect on COVID-19 viral dynamics is still uncertain but is suggested to include its non-specific inhibition of the NACHT, leucine-rich repeat, and pyrin domain-containing protein 3 (NLRP3) inflammasome." (PMID 37767472, 2023). "Moreover, IL-1β is also associated with COVID-19 pathogenesis, and the NOD-like receptor family pyrin domain-containing 3 (NLRP3) inflammasome, which promotes the production of active IL-1β, is activated in COVID-19 patients." (PMID 37515185, 2023). "The robust activation of NLRP3 inflammasome may aggrandize inflammation in patients with severe COVID-19, culminating in worse clinical results." (PMID 37251383, 2023). "This third pathway of CpG-induced MAS through constitutive NLRP3 activation, may be the central pathomechanism of COVID-19." (PMID 36823262, 2023). "The NLRP3 inflammasome has been reported to play an important role in COVID-19 pathogenesis." (PMID 36677800, 2023). "Given the involvement of the NLRP3 inflammasome in MS, COVID-19, and reactivation of EBV from latency, the inflammasome may emerge as a common therapeutic target." (PMID 37112929, 2023). "Since NKG7 is important for cytotoxic degranulation and downstream inflammation and NEAT1 is an activator of the NLRP3 inflammasome, their downregulation may indicate an induced shift away from an inflammatory state in COVID-19 patients." (PMID 36992700, 2023). "In addition, the formation of NLRP3-ASC puncta was detected in monocytes derived from COVID-19 patients." (PMID 36703213, 2023). "Moreover, NLRP3 inflammasome activation correlates with the severity of disease in COVID-19 patients and plays a central role in this excessive inflammatory response." (PMID 36936774, 2023). "Pirfenidone, an approved drug for the treatment of idiopathic pulmonary fibrosis, could inhibit the assembly of NLRP3 inflammasome and alleviate lung inflammation and the duration of hospital stay in COVID-19 patients." (PMID 37251383, 2023). "However, the interaction between COVID-19 and CHIs at the level of NLRP3-inflammasomes needs to be verified by large-scale experimental and clinical studies." (PMID 37383608, 2023). "Finally, our results suggest that these key genes are mainly related to NLRP3 inflammasome in severe COVID-19 patients." (PMID 37113134, 2023).
COVID-19 (continued). "SARS-CoV-2 modulates the NLRP3 inflammasome, especially in COVID-19/AIDS syndemic." (PMID 37243203, 2023). "Indeed, autopsy of COVID-19 patients revealed the presence of active NLRP3 in their peripheral blood mononuclear cells (PBMCs) and tissues." (PMID 37360532, 2023). "Furthermore, inhibiting the activation of NLRP3 or the formation of NETs by SARS-CoV-2 can be considered as a new potential strategy for the treatment of COVID-19 using natural compounds such as curcumin." (PMID 36677800, 2023). "ROS is involved in the inflammatory response in COVID-19 and activation of NLRP3." (PMID 36034662, 2022). "Additionally, microscopy of monocytes and lung tissue samples from patients with COVID-19 show the formation of NLRP3 and ASC puncta, suggesting the formation of NLRP3 inflammasomes in these patients." (PMID 36419185, 2022). "Indeed, inhibition of the NLRP3 inflammasome with the well-characterized NLRP3 inhibitory compound MCC950 reduced COVID-19 pathology in mice." (PMID 35626754, 2022). "Therefore, Vestitol, Pachypodol and I-SPD in Xuanfei Baidu Granules (XFBD) can effectively alleviate the clinical symptoms of COVID-19 patients through NLRP3 and CSF2." (PMID 36034710, 2022). "Indeed, in a recent study, two other NLRP3 SNPs, NLRP3 rs10157379 and rs10754558 polymorphisms, were associated with an important role in severe acute respiratory syndrome (SARS) and severe and critical COVID-19." (PMID 36105941, 2022). "In parallel, these observations have suggested that the NLRP3 inflammasome and IL-1β may aid the innate immune memory after recovery from COVID-19 and contribute to the immunogenicity of SARS-CoV-2 vaccines." (PMID 36209522, 2022). "Anti-inflammatory and NLRP3 inflammatory body inhibitors could be potential therapeutic drugs for COVID-19." (PMID 35165525, 2022). "The World Health Organization declared that currently approved medications (e.g., clozapine, glyburide, carbetapentane) could be used for the treatment of COVID-19, by targeting the NLRP3 inflammasome and autophagy to inhibit the propagation of SARS-CoV-2." (PMID 35639261, 2022). "Interestingly, inflammatory condition of patients with COVID-19 has been related to NLRP3 inflammasome." (PMID 35812405, 2022). "Peripheral blood mononuclear cells (PBMCs) derived from severely ill COVID-19 patients display elevated expression of highly active NLRP3 inflammasome, as reflected by abundant levels of cleaved caspase-1 as well as mature IL-1β and IL-18 released upon stimulation in vitro." (PMID 36209522, 2022). "In summary, our results suggested that COVID-19 plasma exosome exposure induces the NLRP3 inflammasome in endothelial cells of distant organs which may be one of the mechanisms of endothelial cell dysfunction and inflammation during severe COVID-19 disease." (PMID 35587188, 2022). "Indeed, circulating monocytes in the patient with COVID-19 vaccine-related myopericarditis exhibited upregulated NLRP3 inflammasome expression and IL-18 production." (PMID 35251049, 2022). "NLRP3 activation in COVID-19 has already been described in tissues of COVID-19 patients." (PMID 36105941, 2022). "A severe course of COVID-19 is associated with a dysregulated immunological response, which could be treated with AT1R antagonists, NRF2 agonists or NLRP3 inhibitors." (PMID 35742820, 2022). "NLRP3 inflammasome activation has also been described in neutrophils of severe COVID-19 patients." (PMID 35720378, 2022). "Therefore, NLRP3 inhibitors have been suggested for as a potential treatment strategy and are currently being explored for management of moderate COVID-19 symptoms (NCT04540120)." (PMID 35144622, 2022). "However, the fact that there is a role for NLRP3 inflammasome pathway with SARS-CoV-2 infection indicates that a potential usage of antagonists or blockers of the NLRP3 pathway in COVID-19 inflammation regulation and control." (PMID 35144622, 2022).
COVID-19 (continued). "Active NLRP3 inflammasome is present in peripheral blood mononuclear cells (PBMCs) and post-mortem tissues of COVID-19 patients, and high expression of its derived products such as Casp1p20 and IL-18 were seen to correlate with disease severity and poor clinical outcome." (PMID 35720378, 2022). "Thus, a potential countermeasure against the development of severe COVID-19 would be to prevent activation of NLRP3 and other inflammatory pathways." (PMID 35052628, 2022). "Hence, it is plausible to deduce that NLRP3 inflammasome is somewhat involved in COVID-19-related cytokine storms." (PMID 35328506, 2022). "As an inflammatory response, NAcht leucine-rich repeat protein 3 (NLRP3) inflammasomes induce the production of several cytokines, which have been confirmed to play major roles in the pathogenesis of several viral diseases, including COVID-19." (PMID 35496320, 2022). "The strength of this study is that the precision nomothetic approach allowed to delineate the effects of inflammation during the acute phase of COVID-19 on the phenome and lowered HR-QoL in Long COVID, and that these effects are mediated by the NLRP3 and oxidative stress pathways." (PMID 36011997, 2022). "However, other authors showed that recombinant SARS-CoV-2 S protein increased NLRP3 protein expression and induction of IL-1β in macrophages from patients with COVID-19 through the up-stream activation of TLR2." (PMID 36498845, 2022). "GO and KEGG pathway analyses showed that inflammation-, immunity-, and infection-associated terms were enriched in db/db mice microglia, such as Il17ra, Il6ra, Cmklr1, Nlrp3, Trem2, Coronavirus disease-COVID-19, Epstein-Barr virus infection, phagosome and NF-κB signaling pathway." (PMID 35721719, 2022). "Our present study showed that the specific NLRP3 inhibitor could effectively reduce the COVID-19 related inflammatory cytokine storm and alleviate lung immunopathology in the mouse model." (PMID 34979342, 2022). "As discussed in Section 5.1, viroporin ion channel activities activate NLRP3 inflammasome, and COVID-19 severe pathology resulting from an overactive immune-inflammatory response can be exacerbated by the activation of NLRP3 in infected macrophages in humanized mouse model of COVID-19." (PMID 35897696, 2022). "The inhibition of NLRP3 has been broadly discussed as a potential COVID-19 treatment method." (PMID 35742820, 2022). "Besides, the majority of proteasome subunits studied (unless PSMB9 and PSME1) positively correlated with NLRP3 mRNA expression in COVID-19 patients." (PMID 35327634, 2022). "As shown in a recent study, activation of the inflammasome in SARS-CoV-2-infected lung-resistant macrophages is the major driver of COVID-19, and the subsequent inhibition of the inflammasome with small molecules targeting NLRP3 or caspase-1 reverses chronic lung pathology." (PMID 35997950, 2022). "There are several possibilities of NLRP3 activation with COVID-19." (PMID 35144622, 2022). "Interestingly, a recent clinical study revealed that circulating neutrophil subsets from COVID-19 patients display reduced intrinsic caspase-1 activity in response to classical NLRP3 inflammasome activators." (PMID 35406754, 2022). "However, there is no data on the potential function of this shed form of the P2X7 receptor in extracellular vesicles, although circulatory exosomes from COVID-19 patients are able to activate the NLRP3 inflammasome." (PMID 35663992, 2022). "Thus, COVID-19 exosomes appeared to trigger IL-1β production through activation of the NLRP3 inflammasome in both of the endothelial cells." (PMID 35587188, 2022). "Several lines of evidence suggest that IL-1 and the NLRP3 inflammasome may play a role in the pathophysiology of COVID-19." (PMID 36209522, 2022). "In addition, the S protein can drive the formation of NLRP3 inflammatory bodies in macrophages of COVID-19 patients and induce them to secrete mature IL-1β, but this does not occur in macrophages of healthy volunteers." (PMID 36389144, 2022).